IL2 (interleukin 2)
Diseases named in the same sentence as IL2 in open-access papers (continued):
Sharing a sentence is not in itself a finding about the gene and the disease.
avian influenza (7 papers, 2009 to 2023). Infection of domestic and wild fowl and other birds with influenza A virus. "Previously, we demonstrated feasibility of this platform for production of avian influenza vaccines bearing a membrane-bound form of chicken-derived IL-2 and GM-CSF." (PMID 19393093, 2009). "The infections of avian influenza (AIV) and duck hepatitis A virus (DHAV) caused an increase in IL-2 in ducks, but the infection of duck plague virus (DPV) caused a decrease in IL-2 levels." (PMID 35891451, 2022). "During the H5N1 avian influenza period, a sharply increase of circulating cytokines (e.g., IL-6, IL-2 and IFN-γ) could be a potential explanation for lymphocyte depletion in died patients." (PMID 34725309, 2021). "The use of L. lactis expressing chicken interleukin 2 (chIL-2) together with avian influenza hemagglutinin (H5) also revealed adjuvant properties of chIL-2, and the study suggests that L. lactis could be a promising candidate as antigen carrier in vaccines against avian flu." (PMID 25750046, 2015). "In contrast, H5N6 VLPs not only elicited higher neutralizing antibody titers, ranging from 640 to 1280, but also induced higher IL-2, IL-4, IL-5, IFN-γ and TNF production, thus indicating that H5N6 VLPs may be a potential vaccine candidate for broad-spectrum H5Nx avian influenza vaccines." (PMID 35632667, 2022).
Cachexia (7 papers, 2016 to 2024). Severe weight loss, wasting of muscle, loss of appetite, and general debility related to a chronic disease. "Cachexia is a comorbidity condition in elderly cancer patients and can impair the host’s ability to tolerate anti-cancer treatments, as seen in the present study by rapid weight loss with IL-2/anti-CD40 immunotherapy for the elderly mice." (PMID 30459812, 2018). "Conversely, in patients with the Sarcopenia/Cachexia phenotype, we observed significantly decreased abundance of IL-1β and IL-2." (PMID 39575261, 2024). "Macrophages were depleted in vivo using F4/80 antibody and mice monitored for response to IL-2/anti-CD40 immunotherapy, as well as weight loss (i.e., cachexia)." (PMID 30459812, 2018). "On the other hand, in a study of the pathophysiology of cachexia in patients with prostate cancer, a serum cytokinome profile of 10 biomarkers (IL-1β, IL-2, IL-4, IL-5, IL-6, IL-8, IL-10, IL-12, IFN-γ, and TNF-α) was evaluated." (PMID 28050120, 2016). "Indeed, mice that received wtTCR(IRES)-transduced T cells - in which the transduced wtTCR chains were linked by an internal ribosome entry site (IRES) sequence – exhibited significant cachexia following IL-2 administration." (PMID 27823582, 2016). "From this profile, when compared to that of the control group, it appears that serum levels of all cytokines were significantly higher in the cachexia group, and six cytokines (IL-1β, IL-2, IL-8, IL-12, TNF-α, and IFN-γ) were significantly higher in the group with advanced Pca without cachexia." (PMID 28050120, 2016). "Furthermore, in elderly, but not young mice, macrophage inhibition prevented the IL-2/anti-CD40 immunotherapy treatment-induced cachexia." (PMID 30459812, 2018).
coccidiosis (7 papers, 2015 to 2023). A parasitic infection caused by Coccidia. "Following primary and secondary coccidiosis, the expression of IL-2 was significantly increased in the duodenum." (PMID 35214673, 2022). "Th1-type cytokines (e.g. IFN-γ and IL-2), relating to cellular immunity, are regarded to be predominant against coccidiosis." (PMID 33602319, 2021). "functions as adjuvant and IL-2 expressing Eimeria parasites are valuable vaccine strains against coccidiosis." (PMID 26082759, 2015). "The involvement of IL-2 in poultry coccidiosis has been reported." (PMID 35214673, 2022). "Chicken IFN-γ and IL-2 were able to effectively improve the DNA vaccines against to coccidiosis." (PMID 33192575, 2020). "This may be the main reason why the expression levels of IFN‐γ, IL‐2 and IL‐17 mRNA were reduced to different degrees when treated with QOL, and it was speculated that the anti‐coccidiosis effect of QOL might not be realized by regulating the expression levels of IFN‐γ, IL‐2 and IL‐17 mRNA." (PMID 36112763, 2022).
colon adenocarcinoma (7 papers, 2009 to 2025). "Similarly, in murine colon adenocarcinoma models, IL-2 liposomes combined with T-activated killer cells enhanced the infiltration of Lyt-2+ lymphocytes into hepatic metastases, resulting in potent antitumor effects." (PMID 40143046, 2025). "Mice implanted with CAIX positive murine colon adenocarcinoma cells CT-26 treated with the fusion protein IL2-Anti-CAIX(XE114)-TNFmut and IL2-Anti-CAIX(F8)-TNFmut showed around 60% reduction in tumor volume compared to the control group injected with PBS after 18 days of treatment." (PMID 35326544, 2022). "We found that IL-2 was at significantly higher levels in oesophageal than rectal and colonic adenocarcinoma TCM, Ang-2 was at significantly lower levels in oesophageal than colonic TCM and bFGF was at significantly lower levels in oesophageal than rectal and colonic TCM." (PMID 32552799, 2020). "Indeed, levels of IL-2, Ang-2 and bFGF across oesophageal, rectal and colonic adenocarcinoma correlated with LPS-induced levels of the DC surface marker CD54." (PMID 32552799, 2020). "Herein, the maintenance of the cytolytic activity of ex vivo TKD/IL-2-activated PBMNC against a classical NK target and the autologous, Hsp70 membrane-positive tumor of a patient with an anastomotic relapse of a colon adenocarcinoma was tested." (PMID 19549307, 2009).
dry eye (7 papers, 2017 to 2023). "Application of bone marrow-derived MSC into the intraorbital gland showed reductions in the IFN-γ and Il-2 cytokines in an inflammation-induced dry eye model of mice." (PMID 36674547, 2023). "Increases of IFN-γ, IL-2, IL-4, IL-5, IL-13 or IL-β1 in SAC; TSLP in both PAC and SAC; and IL-17, IL-21 and IL-22 in dry eyes have been observed in different studies." (PMID 35935953, 2022). "In addition to the better-known inflammatory function of IL-2 and IFN-γ, there has been observed increases of the pro-inflammatory cytokine IL-6 in dry eye patients." (PMID 29235530, 2017). "In addition, in the BAC induced dry eye murine model, some signs of dry eye disease, such as decreased tear production, low goblet cell density, and pro-inflammatory cytokine induction were observed, but have not yet been validated for CD4 + T cell or IL-2 introduction." (PMID 31738791, 2019).
Ewing sarcoma (7 papers, 2005 to 2024). A small round cell tumor that lacks morphologic, immunohistochemical, and electron microscopic evidence of neuroectodermal differentiation. "In the present study, we present preliminary data that OX40L transgenic EFT cells not only preserve expression of typical Ewing sarcoma-associated antigens but also might enhance the immune response against EFT cells in combination with IL-2 and stimulation of CD137." (PMID 26579494, 2015). "Interleukin-2 (IL-2) transgenic Ewing sarcoma cells can induce tumor specific T and NK cell responses and reduce tumor growth in vivo and in vitro." (PMID 26579494, 2015). "In our previous investigations, we observed activation of T and NK cells by IL-2 transgenic Ewing sarcoma cells." (PMID 26579494, 2015). "OX40L-expressing tumor cells showed a trend for enhanced immune stimulation against Ewing sarcoma cells in combination with IL-2 and stimulation of CD137." (PMID 26579494, 2015). "In these studies, tumor remission was noted only in one patient with Ewing's sarcoma where IL-2 was concomitantly administered." (PMID 15647119, 2005). "Our data suggest that OX40L-expressing tumor cells might enhance immune response against Ewing sarcoma cells in combination with IL-2 and activation of the CD137/4-1BBL co-stimulatory pathway." (PMID 26579494, 2015).
fibromyalgia (7 papers, 2014 to 2025). A chronic disorder of unknown etiology characterized by pain, stiffness, and tenderness in the muscles of neck, shoulders, back, hips, arms, and legs. "The first study on this topic referred to the altered interleukin-2 (IL-2) secretion in patients with primary fibromyalgia syndrome." (PMID 32054062, 2020). "CD4+ T cells from patients required a higher concentration of the mitogen concanavalin A in order to reach optimal secretion of IL-2, thus indicating a lower response of CD4+ T cells from fibromyalgia patients to activating stimuli." (PMID 32054062, 2020). "LDN has been demonstrated to block TLR-4 in macrophages and microglia, inhibit or reduce T-cell proliferation and increase phagocytic activity of macrophages by raising IL-2 and TNF-α concentration and is therefore considered effective in chronic inflammatory disorders like fibromyalgia." (PMID 40337423, 2025).
follicular lymphoma (7 papers, 2016 to 2025). Follicular lymphoma is a form of non-Hodgkin lymphoma characterized by a proliferation of B cells whose nodular structure of follicular architecture is preserved. "Likewise, sIL-2Rα modulates IL-2-mediated immune response in patients with follicular lymphoma." (PMID 27876012, 2016).
gastritis (7 papers, 2009 to 2025). Inflammation of the stomach. "It has been previously demonstrated that FOXP3+ thymocytes are dramatically reduced in IL-2/IL-2R deficient mice and that neutralization of IL-2 using αIL-2 monoclonal antibody results in autoimmuno gastritis in mice." (PMID 23864893, 2013). "As Th1 cells are producers of IFN-γ, a major risk factor in the development of gastritis, and IL-2, which is important for T-cell proliferation and hence bacterial clearance, a Th1 response usually increases gastritis severity and leads to lower colonization densities." (PMID 27322323, 2016). "IL-2 helps activate T cells and NK cells, leading to effective pathogen clearance in H. pylori-infected gastritis." (PMID 41376630, 2025). "The levels of IL-2, IL-17A, IL-17F, IL-22, TNF-α, and IFN-γ were significantly higher in patients with mild and moderate gastritis than Hp- group (P≤0.05)." (PMID 39807418, 2024). "Accordingly, IL-2, IL-17-A, IL-17F, IL-22, TNF-α, and IFN-γ showed significant increases in patients with mild and moderate gastritis compared with the Hp- subjects." (PMID 39807418, 2024). "The amounts of IL-2, IL-4, IL-17A, IL-17F, IL-22, TNF-α, and TFN-γ were significantly different in patients with gastritis compared with Hp- subjects." (PMID 39807418, 2024). "Higher levels of IL-2 (p = 0.001) and ET-1 (p = 0.010) were observed in patients without gastritis compared with healthy controls." (PMID 32947843, 2020). "Patients with atrophic gastritis presented significant lower levels of IL-2, IL-9, IL-6, TGF-β, GM-CSF, IL-17 and ET-1 (p < 0.005) compared to patients without gastritis." (PMID 32947843, 2020). "Patients with atrophic gastritis showed significant lower levels of many cytokines (IL-2 (p = 0.036), IL-9 (p = 0.001), IL-6 (p = 0.038), and TGF-β (p = 0.015) GM-CSF (p = 0.001), IL-17 (p = 0.001) and ET-1 (p = 0.001)) compared to patients without gastritis." (PMID 32947843, 2020).
herpes zoster (7 papers, 2020 to 2025). A common dermal and neurologic disorder caused by reactivation of the varicella-zoster virus that has remained dormant within dorsal root ganglia, often for decades, after the patient's initial exposure to the virus in the form of varicella (chickenpox). "The fluid in skin blisters and peripheral blood of herpes zoster patients has low levels of the Th1 cytokines interleukin (IL)-2 and tumor necrosis factor-α and high levels of the Th2 cytokines IL-10 and IL-4 compared with the levels of these cytokines in samples from a control group." (PMID 32944021, 2020). "The results indicated that FR-gE with XUA01 generated high amounts of IFN-γ and IL-2, comparable to those induced by Shingrix and significantly higher than the other two live attenuated vaccines, suggesting that FR-gE holds potential as an immunogen candidate for a herpes zoster vaccine." (PMID 39337359, 2024). "A robust VZV-specific cell-mediated immunity is required to prevent herpes zoster, thus we used ELISPOT assay to evaluate the induction of gE-specific splenocytes secreting IFN-γ or IL-2 by all vaccine candidates two weeks after boost immunization." (PMID 39081325, 2024). "In addition, under the stimulation of the peptide library, the results of the negative control group and the adjuvant control group were negative, and the specific T cells secreted IFN-γ and IL-2 in the experimental group injected with recombinant herpes zoster vaccine." (PMID 41295497, 2025).
Hypoalbuminemia (7 papers, 2013 to 2024). The concentration of albumin in the blood circulation is below the lower limit of normal. "Common adverse events included post-treatment fever and abdominal pain with IPCGOR combined with IL-2 treatment; increased liver enzymes, hypoalbuminemia, and hand-foot syndrome, among others." (PMID 38434976, 2024). "In addition, previous studies have reported that IL-2 increases endothelial cell permeability, which induces hypoalbuminemia in patients." (PMID 37711172, 2023). "In digestive tumors common biochemical parameters used were: albumin (alone or hypoalbuminemia), carcinoembryonic antigen (CEA), cancer antigen 19–9 (CA19-9) and interleukins (IL-6, IL-8, IL-2)." (PMID 26717416, 2015). "The result of hypoalbuminemia in patients with cancer might be due to cancer patient, pro-inflammatory cytokines (TNF-α, IL-2, and IL-6) induced positive acute phase reactant synthesis compete for nutrient in liver leads to decreases in serum albumin production." (PMID 36869395, 2023).
mastocytosis (7 papers, 2017 to 2025). A clonal myeloproliferative neoplasm characterized by the proliferation and accumulation of neoplastic mast cells in one or multiple organs or organ systems. "Airway mastocytosis was reduced in MC-deficient KitW/W-v mice along with reduced levels of IgE, IL-2, IL-9 and TGF-β." (PMID 28090087, 2017). "C57BL/6 mice pretreated with IL-18 and IL-2 developed mucosal mastocytosis and had high levels of serum mMCP1 (mouse mast cell protease 1), an activation marker of mucosal mast cells." (PMID 30717382, 2019). "Because IL-3 and IL-9 induce mucosal mastocytosis, we examined the capacity of mice injected with IL-2 and IL-18 to protect against infection with S. venezuelensis." (PMID 30717382, 2019). "We found that C57BL/6 mice pretreated with IL-18 and IL-2 developed mucosal mastocytosis with high levels of serum mMCP1, an activation marker of MMC, and became able to promptly expel the intestinal nematode Strongyloides venezuelensis." (PMID 29731751, 2018). "Because IL-3 and IL-9 induce mucosal mastocytosis, we examined whether the animals developed mucosal mastocytosis after treatment with IL-2 and IL-18." (PMID 29731751, 2018). "Etiology of uremic pruritus may comprise several factors, including xerosis, peripheral neuropathy, mast cell hyperplasia, increased serum level of histamine, vitamin A, parathyroid hormone (PTH), and certain inflammatory factors, such as interleukin-2 (IL2)." (PMID 34367296, 2021). "In human fascioliasis, in the acute phase, a predominant Th2 response takes over, with production of IL-4, IL-5, as well as mastocytosis, hypereosinophilia and IgE production and the absence of IFN-gamma and IL-2." (PMID 40864127, 2025).
metabolic syndrome (7 papers, 2016 to 2024). A cluster of metabolic risk factors for CARDIOVASCULAR DISEASES and TYPE 2 DIABETES MELLITUS. "Of note, metabolic syndrome was also associated with lower levels of IL-2 (−2.81 pg/mL), IL-7 (−17.7 pg/mL) and IL-10 (−2.18 pg/mL)." (PMID 39404367, 2024). "VA treatment has been shown to normalize the production of IL-2 and TNFα in mesenteric gut-associated lymph nodes after mitogen stimulation in this rodent model of metabolic syndrome." (PMID 26891736, 2016). "Kermani and coworkers demonstrated that C. sativus (100 mg/day) reduces VEGF, IL-2, and IL-1β while enhancing IL-10 levels compared to the placebo group in metabolic syndrome patients." (PMID 34956439, 2021). "Recent study on PAHs exposure in small population suggested elevation of inflammation (IL2, IL6, IL8) and oxidative stress marker (MDA) in prediabetic patients, indicating a metabolic syndrome enhanced oxidative damage." (PMID 35844632, 2022). "The increasing trend of IL-6 and Il-1β can be explained by antipsychotics (especially atypical antipsychotics) side effects such as metabolic syndrome in the long period, as increased levels of IL-6, IL-1β, TNF-α, IL-2, IFN-γ, and IL-4 have been reported in patients with metabolic syndrome." (PMID 31908647, 2019).
myelodysplastic syndrome (7 papers, 2014 to 2023). A clonal hematopoietic disorder characterized by dysplasia and ineffective hematopoiesis in one or more of the hematopoietic cell lines. "transfused IL-2-activated haploidentical NK cells after cyclophosphamide and fludarabine conditioning and total lymphoid irradiation in relapsed/refractory myelodysplastic syndrome (MDS) and AML patients, and did not use subcutaneous IL-2 post-infusion." (PMID 37654497, 2023). "Next, we describe our phase I/IIa clinical trial protocol to investigate the safety and efficacy of RNK001 cells in patients with AML or myelodysplastic syndrome with excess blasts (MDS-EB2) with residual disease, with and without in vivo IL2 cytokine support (EudraCT 2019-001929-27)." (PMID 37477653, 2023).
peritonitis (7 papers, 2012 to 2025). Inflammation of the peritoneum (tissue that lines the abdominal wall and covers most of the organs in the abdomen). "On the basis of these results, conservative management with peritoneal perfusion of IL-2 and normal saline was an effective approach to prevent peritoneal seeding and peritonitis." (PMID 35391745, 2022). "Increased interleukin-2 (IL-2) production and receptor activity have been demonstrated in arginine-supplemented animals, while a favourable impact on survival has been shown in animal models of peritonitis." (PMID 38540660, 2024).
schistosomiasis (7 papers, 2016 to 2025). An infectious disease caused by parasitic trematodes of the genus Schistosoma that colonize human blood vessels and release eggs that can cause granulomatous reactions leading to acute (swimmer's itch or acute schistosomiasis syndrome) or chronic disease. "The Th1/Th2 cytokines in chronic patients were not significantly different from those in healthy people, while patients with advanced schistosomiasis had higher levels of IL-2, IL-23 and IL-27 and lower levels of IL-18 and IFN-γ." (PMID 37887717, 2023). "Specific cytokines, in particular IL-2, IL-4, IL-5, IL-10, and IFN-ɤ have been implicated in regulation of granulomatous response on schistosomiasis." (PMID 27378927, 2016). "However, one study suggested that administration of IL-2 enhances the severity of fibrosis development in the schistosomiasis model." (PMID 34161342, 2021).